EPCAM (epithelial cell adhesion molecule)
Diseases named in the same sentence as EPCAM in open-access papers (continued):
Sharing a sentence is not in itself a finding about the gene and the disease.
cervical carcinoma (continued). "All of these in vitro and in vivo experiments demonstrated that Slug could trans-suppress EpCAM expression in cervical cancer cells." (PMID 33691694, 2021). "All of these results indicated that Slug inhibited EpCAM expression in cervical cancer cells." (PMID 33691694, 2021). "In addition, this study revealed a trans-suppression effect of Slug on EpCAM through its binding of the proximal promoter region of EpCAM in cervical cancer cells." (PMID 33691694, 2021). "Therefore, the central question is whether there is a potential interaction mechanism between SNAI2 and EPCAM in regulating the stem-like phenotype in cervical cancer cells." (PMID 36674577, 2023). "In order to explore whether the alteration of EPCAM under SNAI2-overexpressing cells was involved in SNAI2 mediating the stemness of cervical cancer cells, EPCAMhigh and EPCAMlow cells were sorted by FACS from SiHa-SNAI2 cells, and then cultured to generate tumorspheres." (PMID 36674577, 2023). "The negative correlation between Slug and EpCAM expression in cervical cancer cells was detected in this study, and linked them with in vitro migration and invasion assay, in vivo metastasis experiments, luciferase reporter assay and Chromatin immunoprecipitation." (PMID 33691694, 2021). "All of these results suggested that SNAI2 blocked the nuclear translocation of β-catenin by inhibiting EPCAM expression, further suppressing the expression of c-Myc and SOX2, and ultimately attenuating the stem-like phenotype in cervical cancer cells." (PMID 36674577, 2023). "In cervical cancer, although it has been reported that inhibition of EPCAM expression significantly increases radiation-induced cell death in a cervical cell line (ME-180), the potential correlation of EPCAM and the stem-like phenotype in cervical cancer cells remains unclear." (PMID 36674577, 2023). "However EpCAM is the most puzzling due to its biphasic effects on the regulation of cell-cell adhesion and EMT during metastasis progression in different types of cancers, and the function of EpCAM in regulating cell motility in cervical cancer remains unclear." (PMID 33691694, 2021). "In blood samples from 7 uterine cervical cancer patients, LVRN‐expressing cells were identified among circulating tumor cells (CTCs) that were enriched by anti‐epithelial cell adhesion molecule (EpCAM) Ab." (PMID 41024351, 2025). "In conclusion, this study reveals a negative relationship between SNAI2 and EPCAM in cervical cancer." (PMID 36674577, 2023). "Thus, in cervical cancer, there is a potential connection between SNAI2 trans-suppression of EPCAM expression and SNAI2-mediated inhibition of the stem-like phenotype." (PMID 36674577, 2023). "This absence of EpCAM under Slug expression in cervical cancer cells probably inhibited cell-cell adhesion and participated in Slug-initiated EMT progression, further enhancing tumor metastasis." (PMID 33691694, 2021). "The in vitro experiments revealed a negative correlation between the expression of Slug and EpCAM in cervical cancer cells." (PMID 33691694, 2021). "The negative correlation between Slug and EpCAM expression in cervical cancer was confirmed by both in vitro and in vivo experiments in this study." (PMID 33691694, 2021). "The absence of EpCAM under Slug expression in cervical cancer cells is probably involved in Slug-regulated EMT and cell growth." (PMID 33691694, 2021). "The absence of EpCAM under Slug expression in cervical cancer cells is probably involved in Slug-regulated EMT." (PMID 33691694, 2021). "Although, a number of monoclonal antibodies to the 32 kDa fragment have been reported, they were never used to study EpCAM expression in cervical cancer." (PMID 29202724, 2017). "In addition, the results of TMA (tissue microarray) also confirmed the negative correlation of SNAI2 and EPCAM protein level in cervical cancer tissues." (PMID 36674577, 2023).
cervical carcinoma (continued). "Therefore, more cases still need to be analyzed to further confirm the negative correlation between Slug and EpCAM in cervical cancer." (PMID 33691694, 2021). "Furthermore, based on the GSE168652 dataset of single‐cell RNA sequencing results of human cervical cancer tissues, we recognized six cancer cell subclusters, which were characterized by negative PTPRC (a marker of immune cells) and positive CDH1, CDKN2A, and EPCAM (markers of epithelial cells)." (PMID 36999964, 2023). "Therefore, whether the absence of EpCAM in cervical cancer cells that resulted from Slug overexpression promotes or inhibits EMT and cell motility, is still unclear." (PMID 33691694, 2021).
hereditary nonpolyposis colorectal cancer (15 papers, 2017 to 2026).
colorectal tumor (14 papers, 2010 to 2025). "In conclusion, we used the 3DISCO/iDISCO+ method to successfully render murine liver tissue optically transparent and immunolabel intrahepatic vasculature using MECA-32 as well as colorectal tumor cells using EpCAM." (PMID 37077833, 2023). "First, we created a 7-plex immunofluorescent staining panel to be used on a colorectal tumor tissue (CRC1) consisting of a tumor marker (EPCAM), T-cell markers (CD3, CD4, and CD8), and myeloid markers (CD163, HLA-DR, and XCR1)." (PMID 37731497, 2023). "EpCAM is an attractive target overexpressed on colorectal tumor cells and slightly expressed on normal tissues." (PMID 35281893, 2022). "Very recently, using the method of flow cytometry, our data showed that HLA-G expression in 157 epithelial cell adhesion molecule (EpCAM) positive-gated colorectal tumor lesions is with a median of 14.90% (range: 1.81~79.90%)." (PMID 34276691, 2021). "Recent studies have demonstrated that the hierarchically organized colorectal tumors compose a small subset of CD133+/EpCAM+ expressing CSCs." (PMID 23826249, 2013). "To this end, and in agreement with earlier reports, we first demonstrated that CD133+/EpCAM+ tumor cells are tumor-initiating CSCs in the studied patient colorectal tumor by conducting the tumorigenesis assay in immunodeficient mice." (PMID 23826249, 2013). "Anti‐EpCAM treatment like EpAb2‐6 could induce apoptosis in colorectal tumor cells, and its combination with atezolizumab, an anti‐PD‐L1 antibody, enhances the cytotoxic activity of CD8+ T cells." (PMID 36341526, 2023). "EpCAM-based FGS of colorectal tumours in combination with FGS of the ureters could enhance the number of radical resections while preserving vital structures." (PMID 27842504, 2016). "Likewise, antibodies against EpCAM can efficiently target colorectal Tumor-Initiating Cells, conferring a considerable value to the EpCAM-isolated CTC population in terms of therapeutic intervention." (PMID 22811761, 2012). "Finally, antibodies against EpCAM can efficiently target colorectal tumour-initiating cells, conferring a considerable value to the EpCAM-isolated CTC population in terms of therapeutic intervention." (PMID 22304365, 2012). "We here show that cytotoxic human T cells engaged by extremely low amounts of an EpCAM/CD3-bispecific antibody construct, which is currently in a phase I trial, have the potential to completely eradicate two kinds of highly tumorigenic colorectal tumor-initiating cells." (PMID 20976159, 2010).
gallbladder cancer (14 papers, 2006 to 2024). "Increased EpCAM levels are typical for epithelium-derived tumors, and EpCAM overexpression in tumor tissue has been associated with poor prognosis in breast, pancreatic, urothelial, and gallbladder carcinoma." (PMID 38928484, 2024). "In breast and gallbladder cancers, high EpCAM expression is associated with poor prognosis." (PMID 36451817, 2022). "High expression of EpCAM is associated with poor prognosis in gallbladder carcinoma." (PMID 23555683, 2013). "Epithelial cell adhesion molecule upregulation was an independent marker for poor survival in lymph node positive breast cancers, and gall bladder cancers." (PMID 16404366, 2006).
small cell lung carcinoma (14 papers, 2011 to 2025). Small cell lung cancer (SCLC) is a highly aggressive malignant neoplasm, accounting for 10-15% of lung cancer cases, characterized byrapid growth, and early metastasis. "Strong EpCAM immunostaining was detected in 85.7, 88.2 and 100% of adenocarcinoma, squamous cell carcinoma and small cell carcinoma of the lung, respectively." (PMID 39199590, 2024). "The use of 5-FU, mitomycin-C or oxaliplatin leads to higher expression of epithelial cell adhesion molecule (EpCAM) and LeY antigen, which is a blood group antigen with a potent expression on the surface of epithelial tumors, including small cell lung cancer." (PMID 35874714, 2022). "Another 99mTc-radiolabelled Fab, nofetumomab (Verluma®) – directed against pancarcinoma glycoprotein antigen epithelial cell adhesion molecule (EpCAM) – was FDA-approved for the diagnosis of small cell lung cancer." (PMID 29156712, 2017). "OH-1 cells representing small cell lung cancer showed in vitro low EpCAM mRNA levels, although they were highly positive for membrane bound EpCAM protein in flow cytometry analysis." (PMID 22590529, 2012). "However, the pathology data show that small cell lung cancer expresses high levels of EpCAM very frequently." (PMID 39199590, 2024). "In small cell lung cancer the Parsortix system showed comparable efficiency to the CellSearch system for enrichment of EpCAM positive cells, but greatly improved recovery of EpCAM negative or EpCAM low expressing cells." (PMID 29152114, 2017).
colitis (13 papers, 2016 to 2025). Inflammation of the colon. "In conclusion, the heterozygous mutation of EpCAM increased the susceptibility to colitis, gut microbiota dysbiosis and liver injury." (PMID 39188786, 2024). "Herein, the heterozygous mutation of EpCAM increased the sensitivity to colitis and exacerbated the dysbiosis of the gut microbiota in the DSS administrated mice because of the impaired tight junctions and the downregulated Pigr." (PMID 39188786, 2024). "In conclusion, the heterozygous mutation of EpCAM increased the susceptibility to colitis, gut microbiota dysbiosis and liver injury of mice." (PMID 39188786, 2024). "The increase of both macrophages and neutrophils demonstrated that the colitis in the DSS-induced EpCAM+/− mice showed the features of both chronic and acute inflammation." (PMID 39188786, 2024). "The overexpression of the pro-inflammatory cytokine IL-6 in the colon indicated the increased sensitivity of EpCAM+/− mice to DSS-induced colitis compared to WT mice." (PMID 39188786, 2024). "EpCAM expression appeared to be as severe as in the AOM/DSS colitis mice, for example, in line with heightened IL-9 levels." (PMID 37275854, 2023). "We also found that the rate of DiO-positive cells in colonic epithelial cells (EpCAM+) and macrophage cells (CD11b+F4/80+) was higher in colitis mice than in normal mice, indicating TDNPs 2 had an excellent targeting ability to colitis mice." (PMID 35488343, 2022). "In contrast to the results in DSS-induced colitis, we detected a few IL-11+ cells expressing epithelial cell markers, such as EpCAM and E-cadherin, in tumor tissues." (PMID 33863879, 2021). "Notably, in the inflamed colon of DSS-induced colitis mice, the uptake of EpCAM+ cells for HA-PLGABilirubin was significantly reduced compared to the normal colon, suggesting compromised epithelial barrier integrity under colitis conditions." (PMID 38169633, 2024). "Finally, it led to the vicious circle between the colitis, gut microbiota dysbiosis and liver injury of EpCAM+/− mice." (PMID 39188786, 2024). "Moreover, exosomes secreted by intestinal epithelial cells after DSS treatment carry a higher amount of TGF-β1 and adhere to the epithelial cell adhesion molecule (EpCAM) expressed by intestinal epithelial cells to alleviate DSS-induced colitis." (PMID 32365813, 2020). "Hence, the downregulation of EpCAM might increase the sensitivity of EpCAM+/− mice to DSS-induced colitis." (PMID 39188786, 2024). "The results showed that, in comparison with control group, VTN was significantly accumulated in extracellular region of epithelial cell labeled by EpCAM in IBD and DSS-induced colitis." (PMID 37501933, 2023). "Still, no EpCAM+ carcinoma cells beyond lamina muscularis mucosae could be clearly detected, and thus increased EpCAM expression in colitis and Tofa 1st colons indicated highly inflamed tissue with T cells and antigen-presenting cells." (PMID 37275854, 2023).
pancreatic adenocarcinoma (13 papers, 2007 to 2025). "Initial functional validation was performed using a Jurkat dual-reporter cell line J–N/N, where we quantified CAR surface expression levels and antigen-specific signaling activation in response to EpCAM positive pancreatic adenocarcinoma cell lines." (PMID 41417221, 2025). "Then, we detected CAR-T cell activation after exposure to EpCAM positive pancreatic adenocarcinoma cells." (PMID 41417221, 2025). "A proliferation assay revealed that two CAR-T cells exhibited distinct proliferation after co-cultured with four EpCAM positive pancreatic adenocarcinoma cells." (PMID 41417221, 2025). "In this cell model, we found that Vav1 is essential for the ATRA induced decrease of the adhesion molecule EpCAM, known to be a marker of pancreatic adenocarcinoma stem cells." (PMID 33165749, 2021). "Immobilised D5.7 induced proliferation in non/low-metastasising rat pancreatic adenocarcinoma, fibrosarcoma, and pheochromocytoma cell lines, which had previously been transfected with EpCAM." (PMID 19002182, 2008). "EpCAM expression was not only seen in 87% of pancreatic adenocarcinoma, but also in 87% of the pancreatic gland." (PMID 17912244, 2007). "Furthermore, EpCAM-sorted pancreatic adenocarcinoma cells from surgically resected tumors could be applied to the analysis of tumor-cell-intrinsic chromatin accessibility patterns." (PMID 36546899, 2022). "Collectively, these data illustrated that EpCAM CAR-T cells were capable of inducing EpCAM specific and potent immune response to pancreatic adenocarcinoma cells." (PMID 41417221, 2025). "EpCAM is expressed in fetal pancreatic tissue and EpCAM+/CD24+/CD44+ pancreatic adenocarcinoma cells were identified as CSCs with potent tumorigenic potential." (PMID 34209658, 2021). "In contrast to ours and these other previously published results, co-expression of EpCAM and Claudin-7 in human embryonic kidney (HEK) cells and in rat pancreatic adenocarcinoma (AS) cells increases ERK activity and cell migration." (PMID 30304739, 2018). "Diffuse membranous staining was found for integrin αvβ6, CEA, cMET, EGFR, HER2, and uPAR in pancreatic adenocarcinoma and integrin αvβ6, CEA, cMET, EGFR, EpCAM, HER2, and VEGFR2 in periampullary adenocarcinoma." (PMID 27130234, 2016). "Previous reports regarding the expression of integrin αvβ6 (85–100 %), cMET (82–100 %), EGFR (36–69 %), EpCAM (56–78 %), HER2 (16–69 %), and VEGFR2 (64–93 %) in pancreatic adenocarcinoma are consistent with our results." (PMID 27130234, 2016). "Two CAR-T cells showed increased release of IFNγ, TNFα, IL-2 and very limited production of IL-6 after stimulated by four EpCAM positive pancreatic adenocarcinoma cells while not by hTERT–HPNE." (PMID 41417221, 2025). "Consistently, two CAR-T cells exhibited potent specific cytotoxicity against four EpCAM positive pancreatic adenocarcinoma cells, while no significant cytotoxic response was observed in hTERT–HPNE." (PMID 41417221, 2025). "In this work, we reported novel EpCAM CAR-T cells with a fully human single-chain variable fragment and evaluated their cytotoxic effects in a panel of pancreatic adenocarcinoma cell lines, three-dimensional tumor spheroid models and patient-derived organoids, and two xenograft mouse models." (PMID 41417221, 2025). "Building upon these findings, we further generated two EpCAM CAR-T cells and verified the tumor-specific immune response, including cell proliferation, upregulation of surface activation markers, cytokine secretion and cytotoxic activity against pancreatic adenocarcinoma cells." (PMID 41417221, 2025). "Therefore, the aim of this study was to explore the suitability of integrin αvβ6, CEA, hepatocyte growth factor receptor (cMET), EGFR, epithelial cell adhesion molecule (EpCAM), HER2, uPAR, and VEGFR2 as molecular targets for tumor-targeted imaging of pancreatic adenocarcinoma patients." (PMID 27130234, 2016).
serous ovarian cancer (13 papers, 2011 to 2025). "High-grade serous ovarian cancer patients had a significantly larger number of EpCAM(+) EVs than the benign controls in serum." (PMID 31212643, 2019). "For example, in high-grade serous ovarian cancer (HGSOC), ALDH1+ or CD133+ CSCs regenerate glandular (EpCAM+/PAX8+) and invasive subpopulations, reconstructing the original tumor’s heterogeneity." (PMID 41009433, 2025). "Among these, DH1, VEGFA, EPCAM, ITGB2, and CLDN7 had the highest correlation scores with serous ovarian cancer." (PMID 36980477, 2023). "Analysis of mRNA suggests very high level of EpCAM and elevated level of HER2 expression in high-grade serous ovarian cancer." (PMID 34439094, 2021).
colon adenocarcinoma (12 papers, 2014 to 2025). "Then we used ELEXO to evaluate EpCAM levels in EVs isolated from the serum of 7 colon adenocarcinoma (CRC) samples." (PMID 34155195, 2021). "Importantly, the elevated AhR protein levels were also found in isolated EpCAM+ tumor epithelial cells, which were prepared from a subset of patient samples diagnosed as colon adenocarcinomas, as well as from the corresponding adjacent normal tissue collected during operations." (PMID 36077780, 2022). "In order to determine the impact of malignant transformation on cellular phospholipidome in colon adenocarcinoma cells, we next performed analyses of PLs and lysoPLs in purified primary tumor and non-tumor EpCAM+ cells." (PMID 34206240, 2021).